CCL5 (C-C motif chemokine ligand 5)
Diseases named in the same sentence as CCL5 in open-access papers (continued):
Sharing a sentence is not in itself a finding about the gene and the disease.
tumor (continued). "Importantly, some of the cytokines and chemokines upregulated in the tumor were also elevated in the plasma of mice receiving heterologous KV vaccine, including increased levels of IFN-γ, CCL5, CXCL10, CCL2, IL-6, CXCL1, and IL-1β one day after VSV-GP-HPV boost." (PMID 34465781, 2021). "Therefore, we hypothesized that CCL5/CCR5 pathway crosstalk between MSCs and tumor cells played a role in the PCa microenvironment." (PMID 34001269, 2021). "Other chemokines upregulated in either the tumour or infiltrating immune cells by CHK1i+LDHU, including CCL5 that directly recruits Tregs or CXCL9, CXCL10, CXCL11 that recruit activated effector, T, NK and NKT cells, as well as Tregs, may also be responsible for the accumulation of Tregs." (PMID 34359633, 2021). "Targeting the host CCL5, via nanoparticle-delivered siRNA, in combination with Maraviroc (an FDA-approved CCR5 inhibitor) resulted in reductions of circulating immunosuppressive monocyte and neutrophils in both 4T1 and PyMT tumor-bearing mice, enhancing robust antitumor responses." (PMID 34572013, 2021). "After neoplasia occurs, more bone marrow-derived monocytes from the blood vessels are recruited to the site of the tumor, where they secrete growth factors and chemokines such as CCL2, CCL5, vascular endothelial growth factor (VEGF), and transforming growth factor beta (TGF-β)." (PMID 34445193, 2021). "CCL5 immunoreactivity was correlated with the aggressive phenotype of breast carcinomas only in the CCR3-positive group, and we speculated that the CCL5-CCR3 interaction might have important role in tumor progression." (PMID 33671956, 2021). "CCL5 and CCL18 up-regulate the activity of various glycolysis factors, including lactate dehydrogenase A (LDHA) and glucose-6-phosphate dehydrogenase (G6PD), which can advance glycolysis in tumor cells, lead to accumulation of lactic acid in TME and restrain the immune system’s anti-tumor reaction." (PMID 34368156, 2021). "Additionally, stromal CCL5 and tumor CCR3 (but not CCR1 or CCR5) expression together are associated with poor outcome in TNBC patients." (PMID 34298673, 2021). "Indeed, within the tumor microenvironment, IL-6 secreted by TNBC cells upregulates CCL5 expression in lymphatic endothelial cells by activating the IL-6 receptor, STAT3, which subsequently enhances transcription of the CCL5 gene." (PMID 34445170, 2021). "Besides, there are DCs attracted by CCL-5, CCL-19, CCL-20, CCL-21, and CXCL-12 chemokines which employ regulatory Tregs and CCR-7+ DC.CCL-17 and CCL-22 working on CCR-4 are capable of straightaway recruiting Th2 and Tregs for tumour progression and spread." (PMID 34336101, 2021). "Finally, 8 genes related to anti-tumor immunity were obtained, which were APOL3, CCL5, CD8A, CD8B, CXCL9, GZMA, GZMK and PRF1.We found that the m6A regulatory factors YTHDC1, YTHDC2, and WTAP were positively correlated with m6A, while IGF2BP3 was negatively correlated." (PMID 34737950, 2021). "Treatment of CT26 syngeneic mouse tumors with the CDK4/6 inhibitor abemaciclib led to an increase in tumor-infiltrating T lymphocytes, and a significant upregulation of T-cell activity, as evidenced by the increased expression of T-lymphocyte activation markers (e.g., IFNG, GZMB, CCL4 and CCL5)." (PMID 33859752, 2021). "Furthermore, CCL5 has previously been shown to play an important role in tumor progression by inhibiting infiltration of CD8+ T cells and increasing the migration of MDSCs into the tumor area." (PMID 33465053, 2021). "When the CCR5/CCL5 signal is disturbed, either by inhibiting CCL5 expression on tumor cells or systemically administrating CCR5 inhibitors, the migration of Treg cells to the tumor microenvironment is reduced, which indicates that the chemokine CCL5 is required for Treg cells migration." (PMID 34977871, 2021).
tumor (continued). "Furthermore, tumor hyperthermia potentiated immune system responses through release of exosomes containing chemokines (CCL2, CCL3, CCL4, CCL5, and CCL20), HSPs, and tumor antigens to the antigen-presenting cells and facilitated tumor cell attack and tumor cell surface modulation." (PMID 34337063, 2021). "Increased secretion of IL-6, TNFα, CCL2, CCL5, CXCL9 and GM-CSF, which are pro-inflammatory factors combined with decreased secretion of anti-inflammatory factors including IL-4, IL-28A, CCL24, CXCL12 and SCF from infected HEL299 fibroblasts, is expected to be tumor-promoting and enhance metastasis." (PMID 34575976, 2021). "On the other hand, CCL5 could also promote antitumor immunity by recruiting CCR5+ activated T cells and DCs to the TME and therefore enhances the immunotherapy response in different tumor types." (PMID 33463063, 2021). "In addition, levels of chemokines (CXCL10, CCL5, IFN-β) were lower in SKIL-overexpressed tumor compared to control, and further TAZ silencing significantly increased chemokine levels in those SKIL-overexpressed tumor." (PMID 33268765, 2020). "Similarly, in stage II BC patients, the positive tumor expression of CCL5 alone or when combined with the absence of estrogen receptor-α significantly increased the risk for disease progression." (PMID 31991604, 2020). "TAM repolarization may be also induced by natural compounds, such as Onionin A, from onions and Deoxyschizandrin, from berries, that can abrogate pro-tumor activation of M2 macrophages and can reduce the production of the tumor-promoting factors (MMP9, CCL5, and VEGF)." (PMID 32354198, 2020). "However, it is currently not known how T cells are recruited to the developing tumor, how they are activated, and how their activation results in microglia Ccl5 production." (PMID 32358581, 2020). "Our present findings demonstrate that irradiated MSCs could recruit macrophages via CCL5 and promote tumor metastasis to non-irradiated organs." (PMID 32382015, 2020). "Chemokine C-C motif ligand 5 (CCL5), also known as Regulated upon Activation, Normal T-cell Expressed and Secreted (RANTES), mediates migration and chemotaxis of cells and is expressed by several cell types such as fibroblasts, epithelial cells, tumour cells and immune cells." (PMID 33116132, 2020). "Interestingly, studies that compared tumours infiltrated by leukocytes (‘hot’) to those that excluded immune cell infiltration (‘cold’) identified more abundant CCL3, CCL4, and CCL5 in hot tumours, including via single-cell transcriptomics that ascribed their expression to CD8+ T cells." (PMID 33046212, 2020). "And among these five types of tumor infiltration immune cells, Tregs was the only one, which not only significantly had effects on survival time but also was significantly related to the expression levels of CCL5 in KIRC." (PMID 33173412, 2020). "Furthermore, CD8 expression was positively correlated with the secretion of CCL5 and CXCL10 in LUAD, indicating that local production of CCL5 and CXCL10 may attract CD8+ T lymphocytes to tumor sites." (PMID 31221150, 2019). "In a recent study we identified a tumor-stroma-inflammation network potentiating multiple processes that contribute to increased metastasis in TNBC; they included expression of pro-metastatic chemokines such as CXCL8 and CCL5, angiogenesis and tumor cell migration and invasion." (PMID 31105691, 2019). "It is also possible that, because CCL5 is sufficient but not necessary for tumor recurrence, it would be preferable to block the induction of the pro-inflammatory program that is induced following Her2 downregulation using agents targeting TNFα or the NFκB pathway." (PMID 30990165, 2019). "Macrophage chemoattractant chemokines MCP-1 (CCL2) and RANTES (CCL5): In a rat model of cancer and in human monocytes in vitro, Josephs and colleagues demonstrated, that IgE crosslinking triggered a TNFα/MCP-1 axis, which resulted in recruitment of macrophages into tumours." (PMID 30956175, 2019).
tumor (continued). "Notably, NK cells produced CCL5 and XCL1, which facilitated cDC1 recruitment to the tumor site." (PMID 31138701, 2019). "Our analysis showing higher CCL5 and CCL7 in BrCa tissues compared to normal tissues indicates that BrCa cells which produce high levels of CCL5 and CCL7 could be responsible for recruiting monocytes in the tumor microenvironment and supporting BrCa progression." (PMID 30850664, 2019). "Our findings implied that irradiation induced the release of CCL5, CXCL9, and CXCL11, which may produce a positive chemoattractant gradient in the tumor microenvironment and facilitate the migration of adoptively transferred T cells into tumor tissues." (PMID 31921127, 2019). "CCL5-expressing pDCs were not present in these tumor tissues (data not shown)." (PMID 30984181, 2019). "However, a recent study using a B16 mouse melanoma model demonstrated that neither Ccr2 nor Ccr5 deficiency affect tumor infiltration of adoptively transferred CD8+ T cells, despite the fact that the tumor expresses high levels of CCL2 and CCL5 (ligands for CCR2 and CCR5, respectively)." (PMID 30483271, 2018). "To provide further evidence on the conclusion that CCL5 suppresses CD8+ T cells accumulation via secreting S100a8/a9, we examined the correlation between the expression level of CCL5 and S100a8/a9 and the number of CD8+ T cells infiltrated in the tumor of CRC patients." (PMID 29991744, 2018). "To investigate whether the two chemokines are necessary for cDC1 recruitment into tumors, we treated WT mice with neutralizing antibodies against CCL5 (αCCL5) and XCL1 (αXCL1) or isotype-matched control antibodies and implanted them with Ptgs1/Ptgs2−/− BRAFV600E tumor cells." (PMID 29429633, 2018). "Notably, the high expression of CCL5 in the tumors of drinkers was not restricted to the cancer cells themselves, but also lymphocytes and epithelial cells which can be found inside the tumor." (PMID 29872080, 2018). "Finally, ACKR5/CCRL2, initially described to promote chemotaxis in response to CCL2, CCL5, CCL7, and CCL8, has also been shown to be involved in tumor metastasization, as its expression has been detected in colorectal cancers and even increases in the early phase of liver colonization." (PMID 30591657, 2018). "Interestingly, IGF-1 maintains secretion of CCL5 from stromal cells, in particular mesenchymal stem cells that are in physical contact with PDAC cancer cells in vitro, resulting in the recruitment of tumor-targeting immune cells." (PMID 29475434, 2018). "The ability of infiltrated immune cells to promote tumor growth, progression, and immune surveillance may be mediated by several pro-inflammatory cytokines and chemokines, including TNFα, interleukin 17 (IL-17), IL-1, and CCL2 and CCL5." (PMID 30154786, 2018). "The greater cell survival benefit in vivo raises the possibility that CCL5 may not solely function in an autocrine manner, but may also recruit monocytes (macrophages/microglia) to the tumor and enhance tumor growth in a paracrine manner." (PMID 28380429, 2017). "Previous study reported that numerous mast cell-related chemoattractants like CCL5, CXCL12, tumor-derived peptides, transforming growth factor (TGF)-β isoforms, fibroblast growth factor (FGF), and platelet-derived growth factor could drive mast cells migration." (PMID 28938626, 2017). "For this reason, we speculated that VEGF production was not stimulated under low CCL5 concentration leading to suppress tumor progression as well as inactivate VEGFR2 signaling after regorafenib dosing." (PMID 27166185, 2016). "However, as autocrine suppression of CCL5 did not result in significant proliferation defects in vitro, any effects on tumor growth and vasculature from suppression of cancer cell CCL5 are likely explained by paracrine signaling to the host microenvironment." (PMID 27863423, 2016).
tumor (continued). "Since RT increases intratumoral CCL2/CCL5 creating a positive chemoattractant gradient in the TME and facilitating migration of IM into the tumor, CVC may also interfere with the extravasation of IM from the blood stream into the tumor." (PMID 27852031, 2016). "Thus, nuclear FAK drives the transcription of Ccl5 and TGFβ2, which are required for recruitment and expansion of immuno-suppressive Tregs into SCC tumors, altering the balance between CD8+ T cells and Tregs in favor of tumor tolerance." (PMID 26406376, 2015). "In addition, the authors do not examine the role of other cell types in the tumor microenvironment which are capable of CCL5 expression." (PMID 26328269, 2015). "Recently, it was demonstrated that mouse tumor-infiltrating granulocytic and monocytic (MO-MDSC) myeloid-derived suppressor cells expressed increased levels of chemokines comprising the CCR5 ligands CCL3, CCL4, and CCL5, and they were responsible to recruit high numbers of Tregs." (PMID 24591756, 2014). "In turn, tumor cells cocultured with PBMC have higher invasion properties than noncocultured cells, and this process is highly inhibited by antibodies to CCL5, suggesting that the cross-talk with PBMC, likely through CCL5, increases the invasion potential of tumor cells." (PMID 24523569, 2014). "Interestingly, distinct effects on virus activity were also observed, in which VV expressing CCL5 or CCL19 resulted in increased persistence within the tumor and more rapid clearance from non-tumor tissues, respectively." (PMID 24967214, 2014). "One possible hypothesis to explain this observation could be that monocytes/macrophages are attracted by the tumor cells to the affected lymph nodes via CCL5 in the absence or relative lack of CD4+ T cells in the blood." (PMID 24244368, 2013). "In addition to the tumor-promoting activities of TNFα and IL-1β that have already been described, it is possible that these two cytokines also have functional interactions with CCL2 and CCL5, by that promoting disease course." (PMID 21486440, 2011). "Accordingly, over-expression of ZEB2 and TWIST1 in surgical samples of both normal and tumor tissues can induce EMT, resulting in over-expression of representative EMT markers VIM, FN, and COLs and membrane signal transducers IL8, CXCL4, CCL5, CXCR4, PDGFRB, and TLR2." (PMID 21533028, 2011). "In contrast, combining TAK-779 treatment with PDGFRβ vaccine failed to considerably reduce the extent of tumor and carcinosis development compared to each treatment alone, again supporting the greatest potential of CCL5 inhibition compared to CCR5 antagonism in this CRC model." (PMID 22205974, 2011). "According to the previously published data, CCL5 increase could contribute to higher metastatic potential of tumor cells rather than the proliferation increase." (PMID 20509882, 2010). "Furthermore, CTCL cells themselves secrete immunomodulatory chemokines such as CCL5 and CCL22, which attract regulatory T cells and M2-polarized macrophages, fostering a highly immunosuppressive microenvironment that promotes immune evasion and sustained tumor progression." (PMID 41614909, 2026). "Moreover, we further confirmed this result in nude mice, and found that that Ccl5 knockdown could not significantly influence the tumor growth phenotype of shKmt5c mice group in nude mice." (PMID 40126333, 2025). "Importantly, the administration of 12C8 inhibited CD147‐K148me2‐mediated CCL5 increase and the CCL5/CCR5 axis‐dependent intercellular crosstalk between tumor cells and macrophages, which decreased the infiltration of M2‐TAMs in tumor tissues and showed a notable anti‐tumor effect in in vivo tests." (PMID 38873823, 2024). "In addition to the increased levels of a macrophage marker in large tumors, our study suggests an association between the mRNA levels of the cytokines CCL5, CCL18, and GDF15, as well as the transcription factor IRF4, and VS tumor volume, which has not yet been investigated in VSs." (PMID 39272860, 2024).
tumor (continued). "Therefore, CCL5 in the tumor microenvironment might be not sufficient to induce CAR-T invasion, requiring external supplementation." (PMID 37660142, 2023). "However, neither CCL5- nor anti-CCL5-neutralizing antibody affected NB cell migration and clone abilities induced by the PTBP2-altered NB cell–monocyte system, indicating that the tumor-inhibiting effect of PTBP2-induced monocytes/Mφs was not determined by the CCL5/CCR5 axis." (PMID 37040518, 2023). "The contradictory results obtained after the inhibition of the CCR5/CCL5 on CD8 T cells and tumor progression might be due to the expression of this receptor/ligand on other cell types, such as immunosuppressive cells, and the proportion of these cells at the tumor site." (PMID 36429101, 2022). "Furthermore, CCR5-CCL4/CCL5 and CXCR3- CXCL9/CXCL10/CXCL11/CXCL13 axis were significantly correlated with CD 4 T and CD 8 T cells, indicating that these interactions may be essential for the recruitment of the T lymphocytes into tumor." (PMID 35530341, 2022). "In contrast, CCL5, CXCL9, and CCL10 were upregulated in the low-risk group; high expression levels of CXCL9 and CXCL10 were correlated with improved OS in most tumors, and anti-PD1 therapy was not beneficial in CXCR3−/− (receptor of CXCL9 and CXCL10) tumor-bearing mice." (PMID 35795712, 2022). "The CCL5/CCR5 axis is the main player in tumor progression, upregulated CCL5 in BCa tissue is one of the factors for facilitating the recruitment and infiltration of macrophages into BCa tissue and recruitment of macrophages into the tumor microenvironment may promote tumor progression." (PMID 35359417, 2022). "Our results demonstrated that the elevated levels of CCL5 and CXCL10 produced by the irradiated tumors might attract the vaccinated CD8+ T cells with a high expression of IFN-γ+CXCR3+ into the tumor, resulting in an increased ratio of CD8+ T cells/Tregs in the tumor milieu." (PMID 33469123, 2021). "In addition, DTYMK could competitively combine with miR-378a-3p to maintain the expression of MAPKAPK2 and thus activate the phospho-HSP27/NF-κB axis, which mediated drug resistance, proliferation of tumor cells, and infiltration of CD163+ M2-type TAMs by inducing the expression of CCL5." (PMID 34795209, 2021). "Interestingly, ELAVL1 (HuR) was shown to modulate the expression of IL-5, IL-6, CCL-5, and TNF-alpha cytokines harboring the HuR-binding motif, which in consequence can influence the cross-talk between HRS cells and the immune infiltration in the tumor microenvironment." (PMID 33544339, 2021). "We also demonstrated that C-C chemokine motif ligand 5 (CCL5) is responsible for maintaining CAF activation, and neutralizing CCL5 could attenuate PARPi-induced CAF activation in vitro and in both BRCA1/2-wild type and BRCA1/2-mutant xenograft models and boost the tumor inhibitory effect of PARPis." (PMID 34108603, 2021). "Indeed, neither M-CSF nor M-CSF+CCL5 stimulation of macrophages promoted tumor cell invasion." (PMID 34298673, 2021). "However, tumor moDCs may also develop and function independently of pre-cDC-derived DCs, as already differentiated circulating cDC1s may accumulate in the TME in response to the production of CCL5 and XCL1 by tumor-infiltrating NK cells, CD8+ T cells, and innate lymphoid cells." (PMID 32486257, 2020). "Lack of Ccl2, Ccl5, and Cxcl10 expression in 4T1ρ0 cells posed the question of whether or not macrophage recruitment into 4T1ρ0 tumors early in their development was compromised, and if so, whether or not this affected tumor formation." (PMID 33329014, 2020). "The results also demonstrated that although CD8+ T cells could not infiltrate into the tumor hypoxic area in either CCL5+/+ or CCL5−/− mice, there were a lot of CD8+ T cells infiltrating into low hypoxic areas in the tumor of CCL5−/− mice but not in those of CCL5+/+ mice." (PMID 29991744, 2018).